CD4 (CD4 molecule)
Diseases named in the same sentence as CD4 in open-access papers (continued):
Sharing a sentence is not in itself a finding about the gene and the disease.
inflammation (continued). "In this review, we focus on the CD4+ T cells in the context of vascular inflammation and describe the evidence supporting the role of different T cell subsets in vascular inflammation." (PMID 25352848, 2014). "The high levels of IL-4 production of PP CD4+ T-cells on day 10 of the EW diet and the moderate intestinal inflammation found in the MLN-ectomized mice suggest that PPs play a role in establishing intestinal inflammation in EW-fed OVA23-3 mice." (PMID 25290461, 2014). "IL–17 is a pro–inflammatory cytokine produced by antigen specific CD4 cells which can enhance a Th1 memory response but potentially also contribute to lung inflammation by attracting neutrophils to lung tissue." (PMID 25549338, 2014). "Higher amounts of HBV/HDV-unspecific CD4 T cells expressing CXCR3 may contribute to the aggravated liver inflammation frequently observed in patients with CHD." (PMID 39980752, 2025). "Interestingly, in chronic intestinal inflammation, CD4+ Trm cells have been found to accelerate the progression of the disease." (PMID 41050652, 2025). "Mouse CCL8 is constitutively expressed in the skin and may contribute to chronic eosinophilic inflammation by inducing the accumulation of CD4+ Th2 cells in a mouse model of chronic AD." (PMID 38840912, 2024). "IL-4-producing CD4+ T cell induction following antigen-dependent T cell priming can significantly influence the development of airway inflammation and hypersensitivity and this, combined with activated inflammatory cells and eosinophils, can cause complex pathologies in an autocrine manner." (PMID 36986643, 2023). "Additionally, the concentrations of CXCL-1, a neutrophil chemoattractant, the frequency of CD4+IL-17+ cells and the pulmonary inflammation were increased in the lungs during the comorbidity compared to the WT OVA group." (PMID 37445595, 2023). "Collectively, Pre-F+G VLP immunization induced high titers of neutralizing antibodies, decreased pulmonary inflammation, reduced eosinophil influx, and enhanced IL-4-producing CD4+ T cells, all of which contributed to inhibiting viral replication in the lungs of mice." (PMID 36986643, 2023). "To verify that the SIRT1–AMPK axis controls allergic inflammation by suppressing mTORC2 activation, we tried to generate knockout mice that were deficient in both AMPK and Rictor in CD4-expressing cells, as Rictor is an important protein involved in the regulation of mTORC2 activity." (PMID 35999454, 2022). "In the current study, we show for the first time that TLR9−/− mice exhibit a low bone mass and low-grade systemic chronic inflammation, which is characterized by the expansion of CD4+ T cells and increased levels of inflammatory cytokines, including TNFα, RANKL, and IL1β." (PMID 35624094, 2022). "Reconstitution of CD4– iNKT cell subset alleviates PM2.5-induced airway inflammation." (PMID 36477357, 2022). "Thus, high doses zinc aspartate control MYC-regulated metabolic gene expression and fitness of CD4+ T cells and prevent from Th1 central autoimmune inflammation and Th2 asthmatic airway inflammation." (PMID 35121767, 2022). "Early ART may normalize levels of MMc to those seen in iHUs through the restoration of maternal CD4+ T cells and/or improvement in systemic immune dysregulation or placental inflammation." (PMID 35550376, 2022). "Accumulating evidence has uncovered that CD4+ T cells are critical for the development and progression of chronic intestinal inflammation, and CD4+ T cell-related cytokines (such as TNF-α, IFN-γ, IL-1β, and IL-17) are upregulated in the inflamed mucosa of patients with IBD." (PMID 32547537, 2020). "Additionally, Exo-d-MAPPS promoted the expansion of immunosuppressive IL-10-producing alternatively activated macrophages, regulatory DCs, and CD4+FoxP3+T regulatory cells in inflamed lungs which resulted in the attenuation of chronic airway inflammation." (PMID 32257769, 2020).
inflammation (continued). "In accordance with these results, intranasal administration of OVA resulted in reduced type 2 airway inflammation as illustrated by reduced number of type 2 cytokine-producing CD4 + T cells, eosinophils, and goblet cell hyperplasia in Zbtb46Cre/+Tslprfl/fl mice." (PMID 32066836, 2020). "Additionally, CBM 588-induced protectin D1 clearly upregulated IL-10-producing CD4+ cells to control antibiotic-induced gut inflammation." (PMID 33193245, 2020). "In addition, we examined the effect deletion of IL-31RA has on lung inflammation and the differentiation of CD4+ T cells." (PMID 30647024, 2019). "Studies showed that LP CD4+ T cells secrete cytokines associated with the development of intestinal inflammation, whereas regulatory T (CD4+CD8a−CD25+Foxp3+) cells in the LP can inhibit cytokine production and the development of intestinal inflammation." (PMID 31370803, 2019). "As T cells are known to play a role in the pathogenesis of airway inflammation, we investigated whether administration of 14BME20 affects CD4+ T cell-mediated immune response during airway inflammation." (PMID 31231389, 2019). "However, data mining of STK32C gene expression changes in Geoprofile datasets GSE26456 or GSE23014 revealed interesting correlations with CD4+ Treg-cell function and lung inflammation." (PMID 26999364, 2016). "Thus, lung inflammation occurs as a consequence of CD4+ T cell recognition of a single alveolar epithelial "self antigen"." (PMID 17610738, 2007). "CD4+ T cells specific for nephritogenic autoantigens are present in the circulation during autoimmune glomerulonephritis, and experimental evidence indicates that CD4+ T-cell-dependent glomerular inflammation can be initiated by T cells responding to antigen located within the vasculature." (PMID 29467472, 2018). "However, enhanced frequencies of P-lig+ CD4+ T cells were reported during intestinal inflammation." (PMID 23630623, 2013). "Moreover, intraocular inflammation was reported to be mediated by activated CD4+ T cells." (PMID 24282811, 2013). "CD4+CD25+FoxP3+ regulatory T cells interact with cells of both the innate and adaptive immune systems to limit acute lung inflammation and promote its resolution." (PMID 41463029, 2025). "Oral inflammation in Rag1−/− mice was induced by the adoptive transfer of CD4+CD25−CD45Rb (high) T cells, and co-transfer of Treg cells with CD4+CD25−CD45Rb (high) T cells inhibited the development of oral inflammation in the mice." (PMID 38515628, 2024). "Allergen-induced airway inflammation and AHR in humans and mice is marked by an influx of inflammatory cells, including eosinophils, neutrophils, and CD4+ lymphocytes that are regulated by and contribute to the release of Th1 and Th2 cytokines." (PMID 39194564, 2024). "The results indicated that both treatments significantly reduced the number of CD4+CD44+ T cells, most of which were memory T cells, in addition to reducing lung inflammation and lower levels of Th2 cytokines, such as IL-4, IL-5, and IL-13." (PMID 39060348, 2024). "Consistent with the results observed in helminth-mediated lung inflammation, after HDM sensitization, there is an increase in the frequency of Rora-expressing Th2 cells and CD103 Rora-expressing CD4 T cells in the lungs." (PMID 37387671, 2023). "Accordingly, in our study, radiological signs of active lung inflammation (like GGO) and GL-ILD treatment itself correlated with increased CD4+ T cells percentage and CD21 low B cells expansion, respectively." (PMID 37548814, 2023). "However, their transcriptome signature and CD4 expression suggest that they may make up a subset of monocyte-derived, rather than tissue-resident, alveolar macrophages that are recruited due to lung inflammation." (PMID 35446789, 2022). "Conjunctival inflammation in acute forms of ocular allergy has increased CCR4+CCR9+ effector T cells, with a diminished frequency of CD4+CD25+FOXP3+ regulatory T cells in peripheral blood." (PMID 33114004, 2020).
inflammation (continued). "In summary, targeting LFA-1 substantially enhanced infiltration of neutrophils, monocytes/macrophages, CD4+ T cells and potentially CD133+ progenitor cells and thereby promoted cardiac inflammation in the EAM model." (PMID 31627327, 2019). "The asthmatic model, used in the previous study, described an in vivo asthmatic mouse model with a distinct sensitization and challenge phase, characterized by OVA-induced airway inflammation and AHR dependent on CD4+ and CD8+ T cells." (PMID 30823378, 2019). "Altogether these results suggest that expression of CCR9 is important for the recruitment of CD4+ T and possibly CD8+ T cells during allergen-induced airway inflammation." (PMID 27795621, 2016). "Lastly, the index patient with the I73T mutation in our previous study displayed a mild interstitial chronic inflammation and most of the infiltrated leukocytes were CD3+ and CD4+ T-lymphocytes." (PMID 21092132, 2010). "Recent data is suggesting that not only CD4+ T lymphocytes, but also CD8+ T lymphocytes, contribute to allergen-induced airway inflammation." (PMID 16740158, 2006). "IL-4 has emerged as a central target, not only for B cell IgE production, but also in the commitment of both CD4+ and CD8+ T cells to cells with Th2 effector function capable of secreting IL-5 resultlng in eosinophilic inflammation." (PMID 18475645, 1995). "Since we recently found that exogenous administration of GSSSG inhibits TCR signaling and protects allergen-induced airway inflammation, reduction of CARS2/CPERS expression in CD4+ T cells may enhance homeostatic proliferation via augmented TCR signaling." (PMID 40303402, 2025). "Ovalbumin (OVA)-specific OT-II; Cas9 CD4+ T cells were activated and transduced with the lipid-targeting sgRNA library and adoptively transferred into Rag1−/− mice, which were then intranasally sensitized with OVA protein to promote lung inflammation." (PMID 40204636, 2025). "In addition, deficiency in IgA (Igha−/−) exacerbates the HFD-induced adipose inflammation and MetS in mice while an enhancement of IgA response through flagellin immunization can prevent HFD-induced MetS in a B and CD4+ T cells-dependent manner." (PMID 40558164, 2025). "Treating CD4+ T cells already in the initial priming phase would have likely evoked similar (or even more significant) protection from EAE and/or asthmatic airway inflammation." (PMID 35121767, 2022). "C57BL/6 mice did not develop lung inflammation and presented higher frequency of CD4+CD25+Foxp3+ Treg cells in the bronchoalveolar lavage fluid (BALF) after the allergen challenge." (PMID 34924814, 2021). "However, as both CD4+ and CD8+ T cells were increased in SA mice, our data highlight a co-operative role for these T cell subsets in AHR and airway inflammation." (PMID 34777398, 2021). "We showed that Ad5-gsgAM-induced CD4+T and CD8+T cells were protective against airway inflammation." (PMID 29302700, 2018). "Although we did not see CD69 and CD11a expression in memory CD4 T cells in the allergen challenged lung, we observed that these cells were sufficient to develop airway inflammation without cell recruitment from the circulation." (PMID 28894184, 2017). "Initially developed by the group of Fiona Powrie, mouse CD4+ T lymphocytes which express high CD45RB (CD4+CD45RBHi) can be adoptively transferred into immunodeficient SCID or RAG1/2−/− mice, where they traffic to the intestine and induce gut inflammation." (PMID 24616886, 2014). "IL-9 production by a subset of non-invariant (type 2) murine CD1d-restricted CD4+ NKT cells is associated with IgE production and antigen-induced pulmonary inflammation and mast cell infiltration." (PMID 22174854, 2011). "The CD4:CD8 ratio represents a surrogate marker of defective T lymphocytes and enhanced immune activation in HIV infection and may characterize a subpopulation with distinct immunological abnormalities and chronic inflammation." (PMID 40437996, 2025).
inflammation (continued). "Expression of c-Met by human CD4+ and CD8+ T cells has also been described, where again c-Met appeared to be a marker of inflammatory circulating T cells; in this case the cells were found at higher frequency in the blood of patients with adaptive cardiac inflammation." (PMID 37520551, 2023). "The cellular branch of the adaptive and innate immune systems appears to be central to the pathogenesis of GCA; autoreactive CD4-positive T lymphocytes, including INF-γ producing T-helper (Th) 1 cells and IL-17-secreting Th17 cells, orchestrate the development of granulomatous vascular inflammation." (PMID 24963300, 2014). "Loss of both IL-4 and IL-5 during OVA-induced airway inflammation did not abolish airway hyperreactivity, which was abolished only after anti-CD4 treatment, suggesting that ST2/IL-33 signaling in CD4 T cells may be critical for efficient antigen-induced airway inflammation." (PMID 28484466, 2017). "Changes induced by endothelial inflammation include the upregulation of adhesion molecules, which, importantly, will also allow non-CMV-specific CD4 T-cells to infiltrate these areas, since adhesion molecules do not discriminate between T-cells of different antigen-specificity." (PMID 33897878, 2021).
cardiovascular disease (146 papers, 2009 to 2026). "Proteome-wide MR identified 11 proteins significantly associated with CAS (p < 3.52 × 10−5), with all but CD4 linked to cardiovascular disease risk." (PMID 40649979, 2025). "Ultimately, except for CD4, all other proteins were associated with the risk of at least two cardiovascular diseases." (PMID 40649979, 2025). "Briefly, PWH 40–75 years of age on stable ART with a current CD4+ T cell count > 100 cells/mm3 and low-to-moderate traditional cardiovascular disease risk were randomized to pitavastatin versus placebo with longitudinal follow-up for cardiovascular events." (PMID 36805331, 2023). "One study found that even a small decrease in the level of CD4+, beneath 500 cells/mm3, is independently associated with the risk of cardiovascular diseases." (PMID 37627941, 2023). "recent low CD4+ values with cardiovascular risk and prognosis of patients who have developed cardiovascular diseases; b." (PMID 37627941, 2023). "At the same time, the optimal ranges of the factors associated with the CD4 count were determined for consideration of the balance between CD4 count management and the risk of cardiovascular disease." (PMID 35276785, 2022). "Although the multivariate analysis showed that a BF% of 25.1% or higher is desirable for a CD4 count of ≥500 cells (mm3)−1, an increase in the BF% is reported to be associated with cardiovascular disease risk." (PMID 35276785, 2022). "For the management of HIV positive individuals, 25% appears to be the optimal BF% when considering the balance between CD4 count management and cardiovascular disease risk." (PMID 35276785, 2022). "The cutoff value of BF% for a CD4 ≥ 500 cells (mm3)−1 and lower cardiovascular disease risk were ≥25.1% and ≤25.5%, respectively." (PMID 35276785, 2022). "This suggests that 25% is the optimal BF% when considering the balance between CD4 count management and cardiovascular disease risk." (PMID 35276785, 2022). "Of note, a persistently low CD4/CD8 ratio is also independently associated with precursor conditions associated with cardiovascular disease (CVD), such as carotid intima-media thickness and arterial stiffness." (PMID 36560606, 2022). "The cutoff values of factors for a CD4 ≥ 500 cells (mm3)−1 and cardiovascular disease risk were obtained by receiver operating characteristic curves." (PMID 35276785, 2022). "A study from Brazil conducted on HIV patients showed that virologic suppression and preservation of CD4 count were important traditional risk factors for cardiovascular disease burden and determining incident cardiovascular disease event risk." (PMID 36440301, 2022). "PWH, despite mostly having an undetectable VL and controlled CD4 count, are at higher risk of cardiovascular disease." (PMID 33801600, 2021). "After adjusting for various confounders like age, sex, and race, the risk factors for cardiovascular disease, persistently low CD4 counts, and high viral loads are also associated with increased risk of SCA and SCD in PLWH." (PMID 33842140, 2021). "A recent study revealed complex associations between of CD4+CD28null T-cells and cardiovascular disease." (PMID 34289931, 2021). "Expansions of cytotoxic CD4+ T cells characterized by loss of CD28 (“CD4+CD28− T cells” or “CD4+CD28null cells”) are closely associated with cardiovascular disease (CVD), in particular coronary artery damage." (PMID 28303136, 2017). "Earlier studies suggest that HIV viral load, CD4+ T-cell count, and antiretroviral therapy are associated with cardiovascular disease (CVD) risk." (PMID 25688354, 2015). "In patients receiving ART, higher T-cell activation has been linked to diminished CD4+T-cell recovery, and surrogate markers of cardiovascular disease and increased mortality." (PMID 25503054, 2014). "Except for CD4, all proteins were associated with cardiovascular disease risk." (PMID 40649979, 2025).